PNMA3 (PNMA family member 3)
Synonyms: MA3; MA5; MGC132756; MGC132758
Tractability: No criterion of Open Targets' tractability assessment is met for any kind of drug.
Gene: Protein-coding gene on chromosome X (153,056,409 to 153,060,467, forward strand). Ensembl gene ENSG00000183837.
Subcellular location: Nucleus, nucleolus
Gene Ontology:
Molecular function: protein binding; nucleic acid binding; zinc ion binding
Biological process: positive regulation of apoptotic process
Cellular component: nucleolus
Homologues: Orthologues: macaque PNMA3 (99% identical), chimpanzee PNMA3 (95% identical), rat Pnma3 (75% identical), mouse Pnma3 (74% identical). Paralogues in human: PNMA5 (41% identical), PNMA2 (37% identical), PNMA1 (37% identical), PNMA6A (35% identical), MOAP1 (34% identical), PNMA6E (33% identical), PNMA6F (31% identical), ZCCHC18 (21% identical), ZCCHC12 (20% identical), PNMA8A (18% identical), PNMA8B (16% identical), CCDC8 (14% identical), and 1 more.
Diseases named in the same sentence as PNMA3 in open-access papers:
PNMA3 is named in the same sentence as 20 diseases in open-access papers, as found by Europe PMC text mining. Sharing a sentence is not in itself a finding about the gene and the disease. The quoted sentences say what the papers report.
melanoma (2 papers, 2012 to 2024). A malignant, usually aggressive tumor composed of atypical, neoplastic melanocytes. "The X‐linked cancer‐related genes that have been associated with melanoma include ZNF280C, IL3RA, PNMA3, NHS, and FGD1." (PMID 38827026, 2024).
tumor (8 papers, 2012 to 2025). "The protein products of the paraneoplastic mammalian antigen-like genes PNMA3 and PNMA5 (Ma3 and Ma5) genes are targets of an autoimmune response triggered by the ectopic expression of antigens in tumor cells." (PMID 27436286, 2016). "Finally, among the genes differentially expressed in opposite directions for the male tumor:tumor-adjacent and female tumor:tumor-adjacent comparisons, the majority still had logFCs less than 1.5, with only LINC01370 and PNMA3 demonstrating logFCs greater than 1.5 in females and none in males." (PMID 39005337, 2024).
PNMA3 also shares sentences with these, for which no sentence is quoted: infection (17 papers); cancer (5); breast cancer (2); lung carcinoma (2); lymphoma (2); mitochondrial disease (2); virus infection (2); bladder cancer (1); bladder tumors (1); Cachexia (1); co-infection (1); HIV-1 infection (1); immune dysfunction (1); leukemia (1); prostate carcinoma (1); sarcopenia (1); Splenomegaly (1); urothelial carcinoma (1).